CFTR (CF transmembrane conductance regulator)
Diseases named in the same sentence as CFTR in open-access papers (continued):
Sharing a sentence is not in itself a finding about the gene and the disease.
chronic obstructive pulmonary disease (continued). "Cigarette smoking causes Chronic Obstructive Pulmonary Disease (COPD), the 3rd leading cause of death in the U.S. CFTR ion transport dysfunction has been implicated in COPD pathogenesis, and is associated with chronic bronchitis." (PMID 24517344, 2014). "By contrast, cigarette smoke exposure and chronic obstructive pulmonary diseases (COPD) reduce CFTR function by poorly defined mechanisms (reviewed in Ref." (PMID 24727471, 2014). "High frequency of the R75Q CFTR variation in patientswith chronic obstructive pulmonary disease." (PMID 36923482, 2023). "We investigate the relationship between rs7512462, a marker of SLC26A9 activity, and lung function pre- and post-treatment with CFTR modulators in Canadian and US CF cohorts, in the general population, and in those with chronic obstructive pulmonary disease (COPD)." (PMID 35396391, 2022). "The dual phosphodiesterase 3 and 4 inhibitor RPL554 (ensifentrine), in clinical development for chronic obstructive pulmonary disease (COPD) and asthma, was shown to activate CFTR with rare class III and IV mutations and was tested in a small phase II trial with promising results (& NCT02919995)." (PMID 35740997, 2022). "Therefore, it is apparent that pharmacological interventions targeted to correct the autophagy-CFTR dysfunction provides a lucrative therapeutic strategy to control chronic obstructive lung diseases pathogenesis." (PMID 32847034, 2020). "A role for CFTR in the pathogenesis of other muco-obstructive airway diseases such as Chronic Obstructive Pulmonary Disease (COPD) has been well established." (PMID 38982492, 2024). "Specifically in the lung, acquired CFTR dysfunction links to augmented tissue inflammation in the HF lung, increased artery vasoconstriction during pulmonary hypertension, and correlates with disease severity during chronic obstructive pulmonary disease (COPD)." (PMID 35055052, 2022). "This impairs CFTR function and leads to the dehydration of the lungs and consequently airway diseases, such as chronic obstructive pulmonary disease (COPD)." (PMID 34832033, 2021). "Nasal CFTR activity in smokers with or without chronic obstructive pulmonary disease (COPD) is significantly impaired and associated with symptoms of chronic bronchitis, suggesting observed changes in response to VG-containing aerosols could potentially lead to reduced MCC in e-cig users." (PMID 36225570, 2022). "These two miRNAs were later shown to be induced by cigarette smoke and further evidence suggests that a chronic cigarette smoking-induced decrease of CFTR expression in chronic obstructive pulmonary disease (COPD) patients is partially mediated by the upregulation of miR-101." (PMID 34947992, 2021). "Pseudomonas aeruginosa virulence factor Cif, found in patients with CF and chronic obstructive pulmonary disease (COPD), suppresses USP10 activity and promotes CFTR ubiquitylation and lysosomal degradation." (PMID 32331485, 2020). "Moreover, chronic obstructive pulmonary disease (COPD) patients had higher pulmonary expression of miR-101, suggesting a link between cigarette smoking, Cd exposure, and suppression of CFTR in COPD." (PMID 32723695, 2020). "We aimed to investigate the regulatory mechanism of lentivirus-mediated overexpression of cystic fibrosis transmembrane conductance regulator (CFTR) in oxidative stress injury and inflammatory response in the lung tissue of mouse model of chronic obstructive pulmonary disease (COPD)." (PMID 31894837, 2020). "Given the well-documented overlap between chronic obstructive pulmonary disease (COPD) and asthma with OSA in the general population, it is plausible that airway muscle dysfunction secondary to CFTR-related abnormalities may contribute to airway instability during sleep in pwCF." (PMID 41562847, 2026).
chronic obstructive pulmonary disease (continued). "While consensus has developed about the importance of carbonaceous nanoparticles in air pollution induced lung diseases like chronic obstructive pulmonary disease (COPD), their specific effect on CFTR and the pathology of CF to the best of our knowledge has not yet been fully elucidated." (PMID 35995803, 2022).
cyst (60 papers, 2010 to 2025). A sac-like closed membranous structure that may be empty or contain fluid or amorphous material. "Chloride enters the cystic cavity through CFTR activated by cAMP, accumulates in the cyst cavity, and sucks sodium and water into the cyst cavity through the paracellular pathway, causing the cyst to enlarge." (PMID 37675342, 2023). "Relevant to this study is that, mirroring the ADPKD cyst inflation process, pkd2 knockdown causes a significant increase in CFTR-mediated fluid secretion into the KV lumen." (PMID 34445719, 2021). "CFTR is a chloride ion channel that is encoded by the CFTR gene whose mutation has been linked to be responsible for the fluid secretion by the thin-walled epithelium of cyst." (PMID 33308138, 2020). "In autosomal dominant polycystic kidney disease (ADPKD), cyst inflation and continuous enlargement are associated with marked transepithelial ion and fluid secretion into the cyst lumen via cystic fibrosis transmembrane conductance regulator (CFTR)." (PMID 26432887, 2015). "While not affecting cell proliferation which is a marked difference to the renal cyst formation, we demonstrate that pkd2-knockdown causes a significant increase in the CFTR-mediated fluid-secretion into the KV lumen mirroring the cyst inflation process." (PMID 26432887, 2015). "Moreover, cAMP increases the fluid secretion (involving cystic fibrosis transmembrane conductance regulator-CFTR) causing cyst growth." (PMID 35328738, 2022). "Interestingly, ADPKD subclusters upregulated the expression of CFTR, which encodes a chloride ion channel thought to be involved in cyst fluid accumulation." (PMID 36310237, 2022). "CFTR, a chloride ion channel, encoded by the CFTR gene whose mutation has been linked to be responsible for the fluid secretion by the thin-walled epithelium of cyst in ADPKD." (PMID 33308138, 2020). "Understanding the molecular mechanisms underlying these dysfunctions has opened the door for innovative therapeutic strategies, including TRPV4 activators, CFTR inhibitors, and calcimimetics, to mitigate cyst growth and preserve renal function." (PMID 40136708, 2025). "cAMP activates the cystic fibrosis transmembrane conductance regulator (CFTR) chloride channel, facilitating chloride ion secretion into the cyst lumen; this ion movement creates an osmotic gradient that draws water into the cysts, leading to their expansion." (PMID 40722668, 2025). "Histone deacetylase inhibitors (HDACi), like trichostatin A, show promise in preclinical models by reducing cyst growth and preserving renal function by enhancing acetylation and suppressing CFTR-mediated fluid secretion." (PMID 40801635, 2025). "Studies showed that loss of pkd1 led to increased expression of TMEM16A and CFTR, as well as enhanced Cl− secretion in murine kidneys, with TMEM16A playing a key role in promoting cyst growth." (PMID 40136708, 2025). "Accordingly, treatment with cAMP analogs increased chloride transport through the CFTR and terminated in fluid secretion and cyst expansion." (PMID 40149611, 2025). "The mechanisms by which cAMP promotes cyst growth are both through inducing water and chloride secretion mediated by the apical chloride channel (CFTR) insertion and also by inducing epithelial proliferation through the ERK/MAPK pathways." (PMID 39940890, 2025). "It has been shown that CFTR inhibitors such as those belonging to the thiazolidinone and glycine hydrazide classes slowed cyst expansion in in vitro and in vivo models of PKD." (PMID 40136708, 2025). "This activation suppresses mTORC1 signaling, reduces CFTR-mediated chloride secretion, and limits tubular cell proliferation and cyst fluid secretion, all of which contribute to cystogenesis in ADPKD." (PMID 41254555, 2025).
cyst (continued). "For instance, kidney organoids exposed to forskolin, an agent that increases intracellular cAMP levels, demonstrate rapid cyst expansion mediated by CFTR-dependent chloride secretion, mimicking one of the core pathophysiological mechanisms in ADPKD." (PMID 40801635, 2025). "VX-809, a corrector of CFTR, was shown to slow cyst growth both in vivo and in vitro and improve the renal function in Pkd1−/− mice." (PMID 40136708, 2025). "Evidence in renal cells also indicates that cAMP stimulation promotes Cl−—driven fluid secretion, specifically by CFTR, leading to cyst expansion." (PMID 40722835, 2025). "In PKD, elevated cAMP activates PKA, which in turn activates the CFTR channel to facilitate the movement of chloride ions (Cl−) into the cyst lumen." (PMID 40136708, 2025). "Overall, by boosting AMPK, these drugs counter metabolic reprogramming: they inhibit mTORC1 and even the CFTR channel responsible for fluid secretion, yielding a dual effect on cyst growth and fluid accumulation." (PMID 40722668, 2025). "Loss or impairment of PC1/2 reduces Ca2+ influx and promotes cAMP accumulation, activating PKA to drive cell proliferation and stimulates cystic fibrosis transmembrane conductance regulator (CFTR)-mediated Cl− secretion, thereby facilitating cyst expansion." (PMID 40852041, 2025). "Recent findings suggested that lipid peroxidation, associated with increased cyst volume, occurred via the chloride channel transmembrane protein 16A (TMEM16A) and cystic fibrosis transmembrane conductance regulator (CFTR)." (PMID 38347570, 2024). "The cAMP then stimulates the activity of the cystic fibrosis transmembrane conductance regulator (CFTR) through which chloride will be transported to the cyst lumen followed by Na+ and water through a paracellular route." (PMID 38339183, 2024). "V2 receptor signaling results in the stimulation of fluid secretion into growing cysts, in part by stimulation of CFTR-mediated chloride transport, and blockade of V2 receptor signaling by V2R antagonists has the potential of slowing cyst expansion." (PMID 37916285, 2024). "Recently, the AMPK activator PF-06409577 demonstrated inhibition of mTOR pathway-mediated proliferation of cyst-lining epithelial cells and reduced CFTR-regulated cystic fluid secretion." (PMID 36876046, 2023). "PKA stimulates cell proliferation by the B-Raf/MEK/ERK signaling pathway, whereas it promotes cyst fluid accumulation through chloride-dependent secretion by the cystic fibrosis transmembrane conductance regulator (CFTR)." (PMID 37763221, 2023). "Inhibitors of Cl− currents such as diphenylamine-2-carboxylate and knockdown of CFTR by antisense oligo-nucleotides inhibited cAMP-activated Cl− currents in cyst cells; 8807590)." (PMID 37686084, 2023). "It is assumed that the major secretory force for cyst fluid secretion is apical cAMP-dependent Cl− secretion, and several studies have suggested CFTR as the essential Cl− channel." (PMID 37686084, 2023). "Fluid secretion depends on the chloride channel of the CFTR and the water channels of the parietal membranes of the cyst wall epithelial cells." (PMID 37675342, 2023). "Apyrase (ATP scavenger) and suramin (P2 receptor inhibitor) reduced cAMP-driven fluid secretion in MDCK cysts while increasing extracellular ATP potentiated cAMP-mediated cyst growth, suggesting a synergistic interaction between CFTR and TMEM16A." (PMID 36120538, 2022). "Apart from cAMP-activated chloride secretion through CFTR, a second mechanism facilitating cyst growth and formation was identified with Ca2+-stimulated chloride secretion by TMEM16A." (PMID 35892566, 2022). "We have previously shown that CFTR channels are functional in embryonic kidneys and are required for cAMP-driven cyst-like tubule expansion." (PMID 35979967, 2022). "Because CFTR is responsible for the fluid secretion into the cyst lumen, we next examined the inhibitory effect of PF‐06409577 on the CFTR function." (PMID 35748097, 2022).
cyst (continued). "This leads to phosphorylation and activation of cystic fibrosis transmembrane conductance regulator (CFTR) to promote Cl− secretion followed by fluid secretion into the cyst lumen." (PMID 35979967, 2022). "PF‐06409577 effectively down‐regulated mTOR pathway‐mediated proliferation of cyst‐lining epithelial cells and CFTR‐regulated cystic fluid secretion, delaying the progression of ADPKD significantly." (PMID 35748097, 2022). "Small-molecule CFTR inhibitors, such as thiazolidinone inhibitor CFTR-172 and phenyl-derivatized glycine hydrazide CFTR inhibitors, were demonstrated to attenuate cyst expansion in both in vitro and in vivo models of PKD." (PMID 35457146, 2022). "LND has been shown to inhibit cAMP-induced CFTR-mediated anion secretion as an open channel inhibitor of CFTR, making it and this class of drugs potential candidates for inhibiting cyst-filling fluid secretion in PKD." (PMID 35979967, 2022). "Fluid secretion into the ADPKD cyst lumen depends upon active electrolyte transport that requires, at least in part, the participation of the cystic fibrosis transmembrane conductance regulator (CFTR) chloride channel." (PMID 35174190, 2022). "Lumacaftor (VX-809 corrector of CFTR) interacts with CFTR protein in the membrane and reduced cyst growth in vitro and in mouse model." (PMID 35328738, 2022). "Both monolayer and cyst populations expressed the core functional transporter genes CFTR, SLC4A2, SCTR, and primary cilia related genes." (PMID 34764255, 2021). "Our positive results reinforce the utility of this ADPKD-cyst-model organ to test the potential of other molecules interfering with CFTR trafficking, stability and activity in preventing ADPKD cyst growth." (PMID 34445719, 2021). "The fluid secretion is driven by cAMP-activated transepithelial chloride transport via the cystic fibrosis transmembrane conductance regulator (CFTR) chloride channel located at apical membrane of the ADPKD epithelial cells lining the cyst." (PMID 33986666, 2021). "Supporting the involvement of CFTR in ADPKD cyst inflation, it was shown that fluid accumulation within cysts involves CFTR-like chloride currents and it is slowed down either through inhibition or knockdown of CFTR." (PMID 34445719, 2021). "Accordingly, steviol can retard cyst expansion in part by reducing CFTR expression via promoting AMPK activity or proteasome-mediated CFTR degradation." (PMID 33986666, 2021). "Although few, there are relevant reports indicating that overexpression of PC1 decreases apical expression of CFTR and showing that cyst-lining cells from ADPKD patients do express CFTR apically." (PMID 34445719, 2021). "It has been demonstrated that cyst expansion is induced by the excessive secretion of Cl− and water into the cyst lumen through CFTR and aquaporins (AQPs) respectively." (PMID 33986666, 2021). "Enhanced proliferation and transepithelial chloride secretion through cystic fibrosis transmembrane conductance regulator (CFTR) and Ca2+-activated TMEM16A Cl− channels is thought to cause an increase in cyst volume." (PMID 32185407, 2020). "Different studies have confirmed that to maintain the integrity of cyst, trans-tubular secretion is required which is facilitated by chloride secretion through the CFTR ion channel that acts as an electrochemical driving force." (PMID 33308138, 2020). "The small molecules like thiazolidinedione CFTR (inh)-172 and GlyH-101, regarded as the novel CFTR inhibitors, have been found to inhibit the fluid secretion in cyst." (PMID 33308138, 2020). "Plasma membrane tethering of the ER by TMEM16A and increase of compartmentalized Ca2+ signals close to the plasma membrane in conjunction with well described Ca2+ dependent modulations of CFTR function provides a mechanism for TMEM16A-dependent cyst formation." (PMID 32859916, 2020).
cyst (continued). "Immunolabelling of TMEM16A and CFTR indicate upregulation of both ion channels in the cyst epithelium of Pkd1−/− kidneys, where both ion channels are strongly colocalized." (PMID 32859916, 2020). "Here we demonstrate that loss of Pkd1 increased expression of TMEM16A and CFTR and Cl− secretion in murine kidneys, with TMEM16A essentially contributing to cyst growth." (PMID 32859916, 2020). "Cystic fibrosis transmembrane conductance regulator (CFTR) is involved in cyst fluid and electrolyte secretion, and mTOR participates in the proliferation of cyst epithelial cells." (PMID 32364526, 2020). "The key characteristic of ADPKD is the development of a large number of the fluid-filled cyst, which is mainly based on CFTR." (PMID 33308138, 2020). "This second messenger cAMP stimulates cyst fluid production by activating chloride (cystic fibrosis transmembrane conductance regulator; CFTR) and water (aquaporin 1) channels on the apical side of the cyst epithelial cells." (PMID 29318424, 2018). "Metformin was shown to suppress cyst growth and fluid secretion through the inhibition of mTOR and CFTR in a previous study using MDCK cell cysts, mouse embryonic kidney explant cultures, and Pkd1 mouse models." (PMID 28769124, 2017). "Cyst growth in ADPKD involves proliferation of the cyst-lining cells and fluid secretion into the cyst lumen due to transepithelial secretion of chloride subsequent to an increase in cAMP mediated by cystic fibrosis transmembrane conductance regulator (CFTR)." (PMID 28197498, 2016). "Not much is known about the molecular mechanisms behind the activation of CFTR in cyst epithelial cells." (PMID 26432887, 2015). "Inhibition of CFTR by small molecule CFTR inhibitors, such as thiazolidinone and hydrazide-containing compounds, has been shown to slow cyst progression in both in vitro and in vivo models of PKD." (PMID 23536832, 2013). "Taken together, the data suggest that steviol retards MDCK cyst progression in two ways: first by directly inhibiting CFTR chloride channel activity and second by reducing CFTR expression, in part, by promoting proteasomal degradation of CFTR." (PMID 23536832, 2013). "This fluid secretion is driven by cAMP-activated transepithelial chloride transport via the cystic fibrosis transmembrane conductance regulator (CFTR) chloride channel located at apical membrane (facing the lumen) of the cells lining the cyst." (PMID 23536832, 2013). "Among these, an increased cAMP concentration is a common finding in different models of ADPKD and cAMP stimulates cyst fluid and electrolyte secretion, possibly involving the stimulation of the cystic fibrosis transmembrane conductance regulator (CFTR)." (PMID 23076254, 2013). "An increase in intracellular cAMP has been shown to stimulate cell proliferation through the MEK/ERK pathway and to activate CFTR-mediated chloride and fluid secretion into the cyst lumen." (PMID 23536832, 2013). "Cyst enlargement in polycystic kidney disease (PKD) involves cAMP-activated proliferation of cyst-lining epithelial cells and transepithelial fluid secretion into the cyst lumen via cystic fibrosis transmembrane conductance regulator (CFTR) chloride channel." (PMID 23536832, 2013). "From these results, we concluded that cyst formation is accompanied by reduced CFTR levels in the MG of Ncadk.i." (PMID 22030022, 2011). "Based on the previous finding that PPARγ agonists inhibit CFTR expression, the current studies were designed to test the efficacy of a PPARγ agonist, pioglitazone, in inhibiting cyst growth." (PMID 21052534, 2010). "Additionally, cAMP activates ion channels such as CFTR and potassium channels, driving electrolyte secretion and water influx into cysts, further contributing to cyst expansion." (PMID 40801635, 2025).